MIR4771-2 (microRNA 4771-2)
Synonyms: hsa-mir-4771-2
Gene: MicroRNA gene on chromosome 2 (111,771,061 to 111,771,134, reverse strand). Ensembl gene ENSG00000266063.
Homologues: Paralogues in human: MIR4771-1 (100% identical).